SLC25A39 (solute carrier family 25 member 39)
Description:
Mitochondrial transporter required for glutathione import into mitochondria. Glutathione, which plays key roles in oxidative metabolism, is produced exclusively in the cytosol and is imported in many organelles. Mitochondrial glutathione is required for the activity and stability of proteins containing iron-sulfur clusters, as well as erythropoiesis.
Synonyms: CGI-69; FLJ22407; CGI69
Tractability: Antibody: UniProt predicts a signal peptide or a membrane-spanning region. PROTAC: ubiquitination databases record sites on it.
Gene: Protein-coding gene on chromosome 17 (44,319,625 to 44,325,801, reverse strand). Ensembl gene ENSG00000013306.
Subcellular location: Mitochondrion inner membrane
Gene Ontology:
Molecular function: 2 iron, 2 sulfur cluster binding; glutathione transmembrane transporter activity
Biological process: cellular response to iron ion; glutathione import into mitochondrion; mitochondrial transmembrane transport
Cellular component: mitochondrial inner membrane; mitochondrion
Genetic constraint (gnomAD): Loss-of-function variants: 46 observed, 48.33 expected, observed/expected ratio (o/e) 0.95, 90% interval 0.75 to 1.22. The upper end of that interval is the gene's LOEUF score, 1.22, which puts it in group 5 of 6, group 1 being the genes least tolerant of losing a copy. Missense variants: 487 observed, 475.05 expected, observed/expected ratio (o/e) 1.03, 90% interval 0.95 to 1.11. Synonymous variants: 218 observed, 192.27 expected, observed/expected ratio (o/e) 1.13, 90% interval 1.01 to 1.27.
Homologues: Orthologues: macaque SLC25A39 (96% identical), chimpanzee SLC25A39 (94% identical), pig SLC25A39 (91% identical), mouse Slc25a39 (88% identical), rat Slc25a39 (88% identical), guinea pig SLC25A39 (82% identical), rabbit SLC25A39 (72% identical), tropical clawed frog slc25a39 (59% identical). Paralogues in human: SLC25A40 (48% identical), SLC25A12 (27% identical), SLC25A13 (25% identical), SLC25A22 (24% identical), SLC25A20 (24% identical), SLC25A29 (23% identical), SLC25A25 (23% identical), SLC25A18 (23% identical), SLC25A28 (22% identical), SLC25A21 (22% identical), SLC25A14 (21% identical), SLC25A23 (21% identical), and 37 more.
Diseases named in the same sentence as SLC25A39 in open-access papers:
SLC25A39 is named in the same sentence as 31 diseases in open-access papers, as found by Europe PMC text mining. Sharing a sentence is not in itself a finding about the gene and the disease. The quoted sentences say what the papers report.
cholestasis (2 papers, 2022 to 2024). Impairment of the bile flow caused by obstruction within the liver, or outside the liver in the bile duct system. "Our study revealed that the expression of Slc25a39/40 changes in mice with cholestasis and LPS-induced inflammation." (PMID 35955707, 2022). "Therefore, the impact of cholestasis on mGSH import, via alterations in SLC25A39/40 expression, needs to be clarified." (PMID 35955707, 2022). "This prompted us to examine the effects of cholestasis using bile duct ligation (BDL) and LPS treatment on SLC25A39/40 expression and GSH levels in the liver and kidneys." (PMID 35955707, 2022).
colorectal cancer (2 papers, 2024 to 2025). A primary or metastatic malignant neoplasm that affects the colon or rectum. "In summary, our findings underscore the essential role of SLC25A39 in promoting ROS-mediated colorectal cancer (CRC) growth and migration." (PMID 39308681, 2024). "In our study, we found that SLC25A39 expression is up-regulated in colorectal cancer (CRC), with higher levels observed in male patients compared to female patients." (PMID 39308681, 2024). "CRABP2 plays a dual role in colorectal cancer: it promotes proliferation and suppresses apoptosis through the nuclear CRABP2/RB1 axis and the cytoplasmic AFG3L2/SLC25A39 axis." (PMID 40305785, 2025). "Similarly, in our current investigation, we observed that the knockdown of SLC25A39 significantly impairs cell survival and migration, strongly implicating the reduction in mitochondrial GSH import mediated by SLC25A39 knockdown in inhibiting cell survival and migration in colorectal cancer (CRC)." (PMID 39308681, 2024).
Parkinson disease (2 papers, 2024 to 2025). A progressive degenerative disorder of the central nervous system characterized by loss of dopamine producing neurons in the substantia nigra and the presence of Lewy bodies in the substantia nigra and locus coeruleus. "In our AD EA TWAS, we also identified genes associated with other neurological and autoimmune diseases, including Parkinson’s disease (CYB561 and SLC25A39), Crohn’s disease (ATG16L1), Amyotrophic lateral sclerosis (SIGLEC9), and Riboflavin Transport Deficiency (SLC52A1)." (PMID 40141087, 2025).
sarcoma (2 papers, 2021 to 2024). A usually aggressive malignant neoplasm of the soft tissue or bone. "Furthermore, mutations in SLC25A39 have been identified in sarcomas." (PMID 39308681, 2024). "In the 255 sarcomas of the TCGA PanCancer Atlas Studies, alterations were found for SLC25A39,GLT8D1 and GATAD2A in 0.78%, 1.57%, and 2.75% of cases, respectively." (PMID 33963205, 2021).
anemia (1 paper, 2024). A reduction in the number of red blood cells, the amount of hemoglobin, and/or the volume of packed red blood cells. "Given the crucial role of glutathione in oxidative metabolism, the expression of SLC25A39 was examined across different groups of congenital anemias." (PMID 39519257, 2024).
breast tumors (1 paper, 2021). "Using AeQTL, we discovered that aggregated rare germline truncations in cis exomic regions are significantly associated with the expression of BRCA1 and SLC25A39 in breast tumors." (PMID 33691015, 2021).
clear cell renal carcinoma (1 paper, 2022). A malignant epithelial neoplasm of the kidney characterized by the presence of lipid-containing clear cells within a vascular network. "In addition, we conducted an in vitro study using human clear cell renal carcinoma (KMRC-1) cells to clarify the mechanism of regulation of SLC25A39/40 expression in the kidneys following LPS treatment." (PMID 35955707, 2022). "Additionally, we used human clear cell renal carcinoma (KMRC-1) cells to elucidate the mechanism of regulation of SLC25A39/40 expression in the kidneys after LPS treatment." (PMID 35955707, 2022).
colon adenocarcinoma (1 paper, 2024). "SLC25A39 was mainly expressed in epithelial cells (colon adenocarcinoma cells), macrophage and tissue-stem cells, which suggested that SLC25A39 might also be involved in regulation of the cellular behavior of macrophage and tissue-stem cells." (PMID 39308681, 2024).
coronary heart disease (1 paper, 2022). "Significantly upregulated were gene regulators of VSMC differentiation, triggers of cell apoptosis, inflammation and coronary heart disease markers (Itih4, Tppp3, Slc25a39, CD44) in parallel to atheroprotective genes such as Morf4l2." (PMID 35163719, 2022).
epilepsy (1 paper, 2020). A brain disorder characterized by episodes of abnormally increased neuronal discharge resulting in transient episodes of sensory or motor neurological dysfunction, or psychic dysfunction. "SLC25A39 resides in susceptibility loci for epilepsy with heterogeneous phenotypes but not as an epilepsy-related gene because its variant has not been identified in families with epilepsy." (PMID 33584793, 2020).
hepatocellular carcinoma (1 paper, 2026). A malignant tumor that arises from hepatocytes. "Solute carrier family 25 member 39 (SLC25A39) is a pivotal mitochondrial glutathione transporter and an emerging oncoprotein in hepatocellular carcinoma (HCC)." (PMID 41977283, 2026).
lung adenocarcinoma (1 paper, 2026). A carcinoma that arises from the lung and is characterized by the presence of malignant glandular epithelial cells. "Reduced AFG3L2 expression in lung adenocarcinoma stabilizes SLC25A39 and enhances oxidative phosphorylation (OXPHOS) and ROS handling, thereby promoting tumor progression." (PMID 41599057, 2026).
metastatic melanoma (1 paper, 2024). A melanoma that has spread from its primary site to another anatomic site. "Next, GSE35640 cohort (treatment with MAGE-A3 immunotherapeutic in metastatic melanoma patients) was applied to validate whether the expression of SLC25A39 could accurately predict the immunotherapy response." (PMID 39308681, 2024).
neuroblastoma (1 paper, 2020). Neuroblastoma (NB) is the most common solid, extracranial childhood tumor. "However, a variant of SLC25A39 was identified in our LGS data, and depletion of SLC25A39 decreased neurite outgrowth in human neuroblastoma cells." (PMID 33584793, 2020). "To examine the effects of SLC25A39 and TBC1D8 on neuronal function, we depleted SLC25A39 and TBC1D8 from the SH-SY5Y neuroblastoma cell line and examined neurite outgrowth." (PMID 33584793, 2020).
tumor (7 papers, 2021 to 2026). "SLC25A40 expression is much lower than SLC25A39 expression, which is increased in many tumor samples compared to the paired normal samples, while SLC25A40 changes are minimal." (PMID 39934670, 2025). "The ESTIMATE results showed that CRC patients with high expression of SLC25A39 had lower immune score, lower stromal score, estimate score, and significantly higher tumor purity, than those in patients with low expression of SLC25A39 (P<0.001)." (PMID 39308681, 2024). "Understanding the implications of SLC25A39 dysregulation in tumor biology is paramount for elucidating novel therapeutic avenues in cancer management." (PMID 39308681, 2024). "These variations affected the following genes: AZIN1 (c.A1099G), COG3 (c.A1903G), COPA (c.A490G), GATAD2A (c.A65G), GLT8D1 (c.C955G) and SLC25A39 (c.C809T), and were all verified by Sanger sequencing on tumors and non-tumor DNA." (PMID 33963205, 2021). "The variations in GATAD2A (c.A65G),GLT8D1 (c.C955G) and SLC25A39 (c.C809T) were validated in all sequenced cases both in non-tumor and tumor samples, showing that these variations were constitutive mutations." (PMID 33963205, 2021). "Moreover, the tumor weight was significantly lighter in the CRC xenografts with SLC25A39 knockdown group compared with the controls." (PMID 39308681, 2024). "Manipulating SLC25A39 function or mitochondrial GSH levels in tumor cells could induce selective oxidative stress, ultimately leading to cell death." (PMID 39308681, 2024). "Additionally, reduced SLC25A39 expression attenuated tumor growth in xenograft models." (PMID 39308681, 2024). "SLC25A39 as well as mitochondrial GSH may also represent promising drug targets for cancer, since manipulating SLC25A39 functioning or mitochondrial GSH in tumor cells may induce selective oxidative stress, leading to cell death." (PMID 35264552, 2022). "Third, no fusion transcript shared by all tumors was found and only variations in three genes were detected both in tumor and non-tumor tissues: SLC25A39 (c.C809T),GLT8D1 (c.C955G) and GATAD2A (c.A65G)." (PMID 33963205, 2021). "Finally, a potential role for SLC25A39 and GATAD2A in tumor development in this patient is weakly supported by literature and the most likely candidate gene appears to be GLT8D1." (PMID 33963205, 2021).
cancer (6 papers, 2021 to 2025). A tumor composed of atypical neoplastic, often pleomorphic cells that invade other tissues. "For example, mechanisms of AFG3L2 and SLC25A39 regulation was just elucidated over the past few years, and it would not be surprising to see these genes upregulated or mutated in cancers to bypass increased oxidative stress at the mitochondria." (PMID 39188677, 2024). "Despite the well-established involvement of mitochondria in cancer, the functional impact of SLC25A39 on CRC progression remains elusive." (PMID 39308681, 2024). "In our investigation, we present a novel finding: SLC25A39 plays a crucial role in cancer cell growth and migration." (PMID 39308681, 2024). "However, the precise impact of aberrant SLC25A39 expression on cellular function in cancer remains unexplored, despite its pivotal role as the primary mitochondrial GSH transporter." (PMID 39308681, 2024). "Additionally, the development of agents targeting SLC25A39 or antibodies that specifically block its channel activity holds promise for therapeutic intervention in cancer metastasis." (PMID 39308681, 2024). "Furthermore, variations in SLC25A39 protein expression among cancer cells may hold prognostic significance for patients, warranting further investigation to ascertain its potential as a cancer biomarker." (PMID 39308681, 2024). "Like other SLC25 family members, SLC25A39 might represent a biomarker for cancer." (PMID 35264552, 2022). "There are various reports that genes involved in this interaction such as SLC25A39, NDST1, and RQCD1 regulate energy metabolism, chemoresistance, and the Akt signaling pathway, respectively, in cancer tissues." (PMID 38627780, 2024). "For our application, classification models predict the known mGSH transporter SLC25A39 but not SLC25A40 as being highly probably related to mGSH metabolism in cancers." (PMID 39934670, 2025). "Since that TXNL4A and SLC25A39 were rarely reported in cancer, we did not discuss them in-depth." (PMID 35096017, 2021).
Hematological Disease (1 paper, 2019). "The network was categorized as “Small Molecule Biochemistry,” “Hematological Disease,” and “Metabolic Disease,” which were composed of down-regulated genes that were listed in the top 2 and 3 networks of A.SW mouse spleen: Gata1-related genes and transporter genes (Abcb6, Slc25a39, and Slc25a37)." (PMID 30941144, 2019).
neurological disorders (1 paper, 2020). "The human SLC25A39 and SLC25A40 mitochondrial carriers could be involved in similar pathways in the brain, considering that they reside in risk loci for epilepsy and that the potentiation of glutamatergic transmission might predispose to neurological disorders." (PMID 32842667, 2020).
SLC25A39 also shares sentences with these, for which no sentence is quoted: amyotrophic lateral sclerosis (1 paper); autism (1); autism spectrum disorder (1); autoimmune disease (1); breast carcinoma (1); Cachexia (1); Crohn disease (1); erythroleukemia (1); metabolic disease (1); microcephaly (1); microphthalmia (1); neurodevelopmental disorder (1); renal carcinoma (1).